TRIT1 (tRNA isopentenyltransferase 1)
Diseases named in the same sentence as TRIT1 in open-access papers (continued):
Sharing a sentence is not in itself a finding about the gene and the disease.
tumor (11 papers, 2014 to 2025). "Specifically, higher levels of TRIT1 were associated with larger tumor sizes (T3) and advanced disease stages (stage III)." (PMID 40391218, 2025). "Following the demonstration of how TRIT1 loss impaired tumor growth, we analyzed its effect on the chemical modification status of A37 using tRNA-associated liquid chromatography–mass spectrometry (LC/MS)." (PMID 33919717, 2021). "To find tumor-associated genetic and epigenetic changes in the A37-modifying enzymes TRIT1 and CDK5RAP1, we data-mined a collection of about 1000 human cancer cell lines in which the transcriptome, DNA methylation landscape, exome sequence, and gene copy number were available." (PMID 33919717, 2021). "This gap currently precludes a comprehensive understanding of TRIT1-mediated immunomodulation in the tumor microenvironment." (PMID 40391218, 2025). "TRIT1, a mitochondrial tRNA modifier and potential tumor suppressor, shows expression changes suggesting complex regulation." (PMID 38534787, 2024). "Furthermore, TRIT1 has been identified as a candidate tumor suppressor gene, with its downregulation observed in various types of cancer and implicated in tumor development and progression." (PMID 40391218, 2025). "Moreover, patients with high expression of TRIT1 had poor prognosis in different tumor stages (especially T2, T1&T2, T3&T2), presence or absence of lymph node metastasis (N0&N1), FA&HA, and HC&Hep subgroups." (PMID 40391218, 2025). "TRIT1 may affect cell homeostasis through the formation of amyloid fibers, thus promoting tumor progression." (PMID 40391218, 2025). "Moreover, this study demonstrated that high TRIT1 levels were correlated with reduced levels of cytotoxic immune cells in the tumor microenvironment, including B cells, cytotoxic cells, and plasmacytoid dendritic cells (pDCs)." (PMID 40391218, 2025). "TRIT1 is a tumor suppressor, which inhibits cell growth and could be responsible for the dwarf phenotype of Tibetan chickens." (PMID 37761812, 2023). "Nearly all of these mutations resulted in amino acid changes in well-known metabolic genes such as LDHB (which is important in glycolysis for the conversion of lactate and pyruvate), TRIT1, which has been proposed as a tumour suppressor and CPT1C, important in fatty acid metabolism." (PMID 28163917, 2017). "TRIT1 is identified as a potential tumor suppressor gene that may be involved in tumor development." (PMID 40391218, 2025). "In vitro and in vivo data indicated that extra TRIT1 copies confer sensitivity to the differentiating drug arsenic trioxide, providing a new candidate therapeutic niche that merits further research, especially for a tumor type with such a dismal clinical outcome." (PMID 33919717, 2021). "The downregulation of TRIT1 levels in these small-cell lung tumors reduced their growth in comparison with shRNA-scramble DMS-273-derived tumors, as demonstrated by the continuous measurement of the tumor volume." (PMID 33919717, 2021). "For example, TRIT1 and ALKBH8 functions are deeply related as mcm5U have been described as i6A dependent, although they are described as a tumor suppressor and oncogene respectively, some hypotheses exist as other functions of the genes but more research are needed to clarify it." (PMID 32241281, 2020).
cancer (8 papers, 2014 to 2025). A tumor composed of atypical neoplastic, often pleomorphic cells that invade other tissues. "Mutations in TRIT1 are associated with mitochondrial disease as well as the progression of some cancers." (PMID 35212379, 2022). "Single-nucleotide polymorphisms of TRIT1 are associated with cancer progression, including increased lymph node metastasis in gastric cancers." (PMID 34361072, 2021). "TRIT1 is a tumor suppressor gene, mutations in which are associated with cancer progression." (PMID 24831542, 2014). "Among these, tRNA isopentenyl transferase 1 (TRIT1) has emerged as a potential crucial factor in cancer development." (PMID 40391218, 2025). "While existing studies suggest that TRIT1 may play a role in cancer development, its specific contribution to LIHC remains unclear." (PMID 40391218, 2025). "Existing research indicates that TRIT1 is significant in the development of certain cancers." (PMID 40391218, 2025). "TRIT1 exhibits pan-cancer overexpression, with significant upregulation in LIHC." (PMID 40391218, 2025). "The final cellular effects of the agent in cancer cells involve induction of differentiation in the case of its approved use in APL which was the most highly enriched gene ontology category in our TRIT1 shRNA experiment." (PMID 33919717, 2021). "Although how nuclear TRIT1 suppresses human cancer remains unclear, research suggests that TRIT1 binds to tRNA in a similar manner to Mod5." (PMID 34361072, 2021). "Furthermore, the high expression of TRIT1 may affect the drug sensitivity and resistance of cancer patients by influencing the expression and function of selenoprotein." (PMID 40391218, 2025).
neurodevelopmental disorder (1 paper, 2020). A behavioral and cognitive disorder with onset during the developmental period that involves impaired or aberrant development of intellectual, motor, or social functions. "I6A37 tRNA hypomodification that results from pathogenic mutations in TRIT1 causes debilitating childhood neurodevelopmental disorders." (PMID 32324744, 2020).
neurological disorder (1 paper, 2021). "Patients with a homozygous pathogenic p.R323Q variant in tRNA-isopentenyl-transferase (TRIT1) show a severe neurological disorder, and hence we wondered whether selenoprotein expression was impaired." (PMID 34768885, 2021). "Since neurological disorders including seizures are also phenotypes observed in several mouse models carrying mutations in tRNA[Ser]Sec, we wondered whether selenoprotein expression was also affected in patients harboring pathogenic TRIT1 variants." (PMID 34768885, 2021).
TRIT1 also shares sentences with these, for which no sentence is quoted: mitochondrial disease (3 papers); infection (2); ovarian carcinoma (2); adenoma (1); brain disorder (1); combined oxidative phosphorylation deficiency 35 (1); diabetic kidney disease (1); Encephalopathy (1); gastric adenocarcinoma (1); hypertrophic cardiomyopathy (1); kidney damage (1); lung adenocarcinoma (1); Menkes disease (1); non-small cell lung carcinoma (1); pneumonia (1); rectal cancer (1); renal fibrosis (1); small cell carcinoma (1).